DYNC1I2 (dynein cytoplasmic 1 intermediate chain 2)
Description:
Acts as one of several non-catalytic accessory components of the cytoplasmic dynein 1 complex that are thought to be involved in linking dynein to cargos and to adapter proteins that regulate dynein function. Cytoplasmic dynein 1 acts as a motor for the intracellular retrograde motility of vesicles and organelles along microtubules. The intermediate chains mediate the binding of dynein to dynactin via its 150 kDa component (p150-glued) DCTN1 (By similarity). Involved in membrane-transport, such as Golgi apparatus, late endosomes and lysosomes (By similarity).
Synonyms: DNCI2; DIC74; IC2; NEDMIBA
Tractability: Small molecule: a structure with a bound ligand is known. PROTAC: ubiquitination databases record sites on it; its protein half-life has been measured.
Gene: Protein-coding gene on chromosome 2 (171,687,409 to 171,750,158, forward strand). Ensembl gene ENSG00000077380.
Subcellular location: Cytoplasm, cytoskeleton; Cytoplasm
Subcellular location (Human Protein Atlas): Centrosome; Cytosol; Flagellar centriole; Microtubules; Mid piece; Principal piece; End piece
Pathways (Reactome):
Cell Cycle: AURKA Activation by TPX2; Amplification of signal from unattached kinetochores via a MAD2 inhibitory signal; EML4 and NUDC in mitotic spindle formation; Loss of Nlp from mitotic centrosomes; Loss of proteins required for interphase microtubule organization from the centrosome; Mitotic Prometaphase; Recruitment of NuMA to mitotic centrosomes; Recruitment of mitotic centrosome proteins and complexes; Regulation of PLK1 Activity at G2/M Transition; Resolution of Sister Chromatid Cohesion; Separation of Sister Chromatids
Vesicle-mediated transport: COPI-independent Golgi-to-ER retrograde traffic; COPI-mediated anterograde transport
Autophagy: Aggrephagy
Cellular responses to stimuli: HSP90 chaperone cycle for steroid hormone receptors (SHR) in the presence of ligand
Disease: HCMV Early Events
Immune System: MHC class II antigen presentation
Organelle biogenesis and maintenance: Anchoring of the basal body to the plasma membrane
Signal Transduction: RHO GTPases Activate Formins
Gene Ontology:
Molecular function: protein binding; dynein heavy chain binding; dynein light chain binding; microtubule motor activity
Biological process: microtubule-based movement; positive regulation of intracellular transport; positive regulation of mitotic cell cycle spindle assembly checkpoint; transport along microtubule
Cellular component: centrosome; cytoplasmic dynein complex; microtubule; vesicle; cytoplasm; cytosol; male germ cell nucleus; cytoskeleton; outer dynein arm
Genetic constraint (gnomAD): Loss-of-function variants: 38 observed, 59.32 expected, observed/expected ratio (o/e) 0.64, 90% interval 0.49 to 0.84. The upper end of that interval is the gene's LOEUF score, 0.84, which puts it in group 3 of 6, group 1 being the genes least tolerant of losing a copy. Missense variants: 386 observed, 613.69 expected, observed/expected ratio (o/e) 0.63, 90% interval 0.58 to 0.68. Synonymous variants: 171 observed, 212.9 expected, observed/expected ratio (o/e) 0.8, 90% interval 0.71 to 0.91.
Homologues: Orthologues: chimpanzee DYNC1I2 (99% identical), guinea pig DYNC1I2 (99% identical), pig DYNC1I2 (99% identical), dog DYNC1I2 (99% identical), rabbit DYNC1I2 (98% identical), mouse Dync1i2 (98% identical), rat Dync1i2 (98% identical), macaque DYNC1I2 (91% identical), tropical clawed frog dync1i2 (89% identical), zebrafish dync1i2b (82% identical), zebrafish dync1i2a (79% identical), Drosophila melanogaster sw (51% identical), and 8 more. Paralogues in human: DYNC1I1 (76% identical), DNAI4 (22% identical), DNAI1 (19% identical), DNAI3 (18% identical), DYNC2I1 (17% identical), DNAI2 (16% identical), DYNC2I2 (16% identical).
Diseases named in the same sentence as DYNC1I2 in open-access papers:
DYNC1I2 is named in the same sentence as 22 diseases in open-access papers, as found by Europe PMC text mining. Sharing a sentence is not in itself a finding about the gene and the disease. The quoted sentences say what the papers report.
glaucoma (1 paper, 2025). Increased pressure in the eyeball due to obstruction of the outflow of aqueous humor. "DYNC1I2 underlies enrichment in an RGC subtype clusters and encodes a dynein-1 intermediate chain; dynein-dependent axonal transport is known to fail early in experimental glaucoma, potentially linking this locus to RGC transport vulnerability." (PMID 41282774, 2025).
glioma (1 paper, 2008). A benign or malignant brain and spinal cord tumor that arises from glial cells (astrocytes, oligodendrocytes, ependymal cells). "These genes had varying degrees of glioma-specific splicing and included APPA4, CLTB, DYNC1I2, NF1, RTN4 and TNC." (PMID 18474104, 2008).
Intellectual disability (1 paper, 2020). "Furthermore, the 2q24-31.1 locus encompasses several other possible genes of interest (e.g. DYNC1I2, responsible for a neurodevelopmental disorder characterized by intellectual disability, spasticity, and neuroradiological anomalies), which were not investigated." (PMID 32705143, 2020).
microcephaly (1 paper, 2024). A congenital or acquired developmental disorder in which the circumference of the head is smaller than normal for the person's age and sex. "In family 12, two affected individuals were found to have a splice donor site mutation (c.607 + 1G > A) in DYNC1I2, which is associated with neurodevelopmental disorder with microcephaly and structural brain anomalies (OMIM 618492)." (PMID 39281811, 2024).
cancer (8 papers, 2011 to 2023). A tumor composed of atypical neoplastic, often pleomorphic cells that invade other tissues. "By characterizing the functional interaction between HHIP-AS1 and DYNC1I2 in cancer cells and in NSC, we unraveled the existence of an additonal layer whereby SHH signaling sustains cell growth and progression." (PMID 35831316, 2022). "We uncover that neither HHIP-AS1 nor the corresponding regulatory element in DYNC1I2 are evolutionary conserved in mice demonstrating the power of cross-entity transcriptome-wide comparisons to identify regulatory lncRNA circuitries in human cancer." (PMID 35831316, 2022).
tumor (5 papers, 2011 to 2023). "Thus, we hypothesized that HHIP-AS1 loss may cause a similar effect in human tumor cells by reducing DYNC1I2 availability." (PMID 35831316, 2022). "More importantly, when we overexpressed DYNC1I2 using CRISPR-Cas9-based activation in HHIP-AS1-transiently depleted cells, both proliferation and viability were restored, indicating that HHIP-AS1 exerts its pro-proliferative effects by controlling DYNC1I2 abundance in tumor cells." (PMID 35831316, 2022).
nervous system disease (1 paper, 2022). "The nervous system disease class consists of proteins APP, DYNC1H1, DYNC1I2, HINT1, LSM2, RNF11, SNCA in between 30% and 40% association." (PMID 34918006, 2022).
DYNC1I2 also shares sentences with these, for which no sentence is quoted: neurodevelopmental disorder (3 papers); basal cell carcinoma (1); Beckwith-Wiedemann syndrome (1); breast carcinoma (1); cancer of female genital organs (1); cancer of male genital organs (1); diabetes (1); infection (1); liver cancer (1); long-QT syndrome (1); medulloblastoma (1); melanoma (1); peripheral nerve injury (1); skin cancer (1); Wilms’ tumour (1).